NF1 (neurofibromin 1)
Diseases named in the same sentence as NF1 in open-access papers (continued):
Sharing a sentence is not in itself a finding about the gene and the disease.
glioma (continued). "Ongoing clinical trials are evaluating the efficacy of MEK inhibition for gliomas in patients with NF-1 (ClinicalTrials.gov NCT03871257)." (PMID 38216572, 2024). "NF1 loss is a marker of RAS/MAPK signaling dysregulation and a putatively targetable event in gliomas, but rapid, accurate identification remains fraught." (PMID 39472976, 2024). "Analysis of Differentially Expressed Genes (DEGs) revealed significant upregulation of several genes in recurrent glioma, including NF1, NIT1, SCXB, and VCAN." (PMID 39554845, 2024). "NF1-related low-grade gliomas have a relatively favorable prognosis compared to that of non-NF1-associated low-grade gliomas." (PMID 39795595, 2024). "We performed an exhaustive literature search for NF1 antibodies previously validated for immunochemistry in human glioma tissue." (PMID 39472976, 2024). "Moreover, CLEC7A exhibits a significant elevation in mesenchymal subtype gliomas, which are distinguished by heightened immunosuppression, increased aggressiveness, and malignant proliferation driven by mesenchymal differentiation resulting from mutations in the NF1 gene." (PMID 38846954, 2024). "Meanwhile, the challenges in generating non-NF1 pLGG models include the low proliferation capacity and the specific permissive tumor microenvironment necessary for glioma formation." (PMID 38318325, 2023). "After BRAF alterations, NF1 mutations are the next common MAPK changes, at approximately 15% of all gliomas." (PMID 37124503, 2023). "Even though patients with NF1 low-grade gliomas share the same tumor pathways with BRAF V600-mutant low-grade gliomas, the administration of these drugs is still mostly limited to clinical trials or off-label use." (PMID 38139220, 2023). "The second clinical case involved a carrier of the de novo NF1 gene mutation who was concurrently diagnosed with alveolar rhabdomyosarcoma (ARMS), juvenile xanthogranuloma, and gliomas located in the central nervous system (CNS), including in the optic nerve." (PMID 37761810, 2023). "use Neurofibromatosis-1 (NF1), a glioma predisposition syndrome, to evaluate the role of microglia in glioma growth." (PMID 38173841, 2023). "As deletion or mutation of the Nf1 gene, which encodes neurofibromin, is associated with poor prognosis in glioma, it underscores the role of CDK5 in promoting glioma via CRMP2." (PMID 37993880, 2023). "Our mouse NF1-HGG cell lines were derived from 3 gliomas that sporadically arose in our NPcis mouse model." (PMID 36730269, 2023). "Namely, the role of secondary mutations in epigenetically driven glioma has only been superficially defined, with an unclear role of key oncogenic driver genes such as EGFR, PTEN, RB1, NF1, TERT, and CDKN2A on modulating the tumor microenvironment." (PMID 37706202, 2023). "Most tumors found in the optic pathway and hypothalamus/midline region were pediatric low-grade gliomas (n = 15, 71%), 3 of those patients were diagnosed with neurofibromatosis 1 (NF1)." (PMID 35147892, 2022). "Apart from BRAF mutations, in glioma, RAS/MAPK signaling can be activated by neurofibromatosis 1 (NF1) gene inactivating mutations or deletions." (PMID 35875139, 2022).
glioma (continued). "A phase II study to confirm the efficacy and safety of trametinib as single agent in NF1-associated LGG and non-NF1 gliomas with either KIAA1549-BRAF fusion or activation of the MAPK/ERK pathway, is ongoing (NCT03363217)." (PMID 35784925, 2022). "To address this need, we have assembled a cohort of 47 gliomas arising in the setting of NF1 and used multiplatform molecular profiling to develop a new classification scheme with prognostic and therapeutic significance." (PMID 35945463, 2022). "Low-grade gliomas arising in the setting of NF1 occur throughout the neuroaxis with a large proportion arising in the optic pathway, cerebellum, and thalamus." (PMID 35945463, 2022). "Malignancies, including gliomas and peripheral nerve sheath tumors (PNFs), occur 4–6 times more commonly in NF-1 patients than in the general population." (PMID 36010360, 2022). "IDH1, CIC, and NF1 have been repetitively reported in gliomas and the preferential distribution of IDH1 in the LGG group verified the clinical classification of our patient cohort." (PMID 35865002, 2022). "This review of optic gliomas-NF1-associated gliomas includes the current approach and knowledge of OPG-NF1 and future directions in OPG-NF1 management." (PMID 36117804, 2022). "For example, PN gliomas are more sensitive to chemotherapy and radiation treatment and NF1-silenced gliomas were shown to be more sensitive to radiation than temozolomide treatment." (PMID 35906213, 2022). "In these mice, neuroligin-3 (Nlgn3) is shed in the Nf1-mutant (Nf1+/neo) optic nerve in an activity-dependent manner, such that genetic or pharmacological blockade of Nlgn3 shedding inhibits glioma initiation and progression." (PMID 35589737, 2022). "Patients with NF1 also harbor a propensity to develop gliomas, both low- and high-grade, the most common of which involve the optic pathway." (PMID 35053664, 2022). "The MES subtype, accompanied by NF1 mutations, which are more common among TMSB10-high glioma samples, was correlated with an abundance of macrophages, stromal activation and the worst prognosis." (PMID 36163046, 2022). "In these studies, Nf1 optic glioma growth in mice requires T cell and microglia support through the elaboration of critical cytokines and growth factors, as Nf1 optic glioma stem cells cannot form glioma-like lesions in mice lacking these stromal cells." (PMID 35986378, 2022). "Furthermore, it could promote tumor growth in both NF1-associated gliomas and other gliomas." (PMID 36357661, 2022). "NS individuals are also at higher risk for cancer, and many of the cancers seen in NF1 are also seen in NS, such as JMML, ALL, neuroblastoma, embryonal rhabdomyosarcoma, glioma and acute myeloid leukemia." (PMID 35103797, 2022). "For instance, TILs are enriched in NF1 and RB1 mutated gliomas but depleted in EGFR-amplified and PTEN-deleted gliomas." (PMID 35203421, 2022). "The understanding of the influence of NF1 on glioma properties as a whole and concerning the tumor microenvironment is still minimal." (PMID 34687436, 2022). "Children with TS develop subependymal giant cell astrocytoma, a specific subtype of astrocytoma, while children with NF-1 show a predilection for optic gliomas, a subtype of PA, while in adulthood patients with NF-1 tend to develop high-grade gliomas." (PMID 33808415, 2021).
glioma (continued). "Aside from NIH criteria, some NF1-related features (gliomas other than OPG, scoliosis, pectus excavatum) and signs of neurological involvement were more common in the A group and in patients with genetic diagnosis." (PMID 33919865, 2021). "For instance, gliomas that occur in NF1 patients are assigned to LGm6, which is a poorly defined methylation class subgroup." (PMID 35008787, 2021). "MEKi selumetinib and trametinib are currently employed in trials for low grade gliomas (LGG) including NF1 patients (NCT03363217, PNOC021, NCT03871257, NCT04166409, NCT04576117, NCT033263388, NCT01089101)." (PMID 33863389, 2021). "For example, the MEK inhibitor selumetinib demonstrated activity in BRAF V600E-mutant, KIAA1549:BRAF fusion positive and NF1-mutant (lower grade) gliomas, providing a rationale for its evaluation in HGAP." (PMID 33905054, 2021). "Selumetinib treatment achieved partial progress in 40% and visual acuity improvement in 20% of NF1 low grade glioma in a phase II clinical trial." (PMID 34359780, 2021). "Altogether, our data support that FOSL1/FRA-1 regulates MES gene expression and aggressiveness in human gliomas via direct transcriptional regulation, downstream of the NF1-MAPK-FOSL1 signaling." (PMID 34399888, 2021). "In a recent animal model, midkine being produced by NF1 mutant neurons activates T lymphocytes and maintains glioma growth." (PMID 35008787, 2021). "Diffuse gliomas with subtype Ims1 displayed higher levels of TMB and mutation number and had more infrequent IDH mutations and more frequent PTEN and NF1 mutations." (PMID 34815785, 2021). "(A) Heatmap of the subtypes single-sample gene set enrichment analysis (ssGSEA) scores and NF1 genetic alterations of the IDH-wt gliomas in the TCGA dataset." (PMID 34399888, 2021). "The ranking of the high grade gliomas by patient representatives was much higher than the ranking by the NF1 experts in the consensus meeting." (PMID 33903738, 2021). "Lastly, NF1 mutant patients with ALT+ gliomas had significantly worse survival than ALT− gliomas with elongated or normal telomeres." (PMID 34069193, 2021). "Yuan Pan and colleagues studied gene expression in four different Nf1-optic glioma models and found a 25-gene expression signature that is shared between all glioma models compared to normal optic nerve." (PMID 34359780, 2021). "The polarization of GAMs to immunosuppressive M2 type is a representative tumorigenic process positively bound up with the grading and rapid recurrence of gliomas, which was widely found in mesenchymal GBM cells and was related to NF1 loss." (PMID 34211978, 2021). "Everolimus (an mTOR inhibitor) has also been recently tested in a phase II clinical trial for treatment of low grade gliomas in patients with NF1 (NCT01158651); however, the results of this clinical trial have not been published yet." (PMID 34359780, 2021). "Reduced immune infiltrates were observed in IDH mutant glioma, while Wang found increased macrophage infiltration in NF1 mutant tumors." (PMID 32392361, 2020). "We then stained archived samples of several different RCAS/tv-a mouse models of glioma including those driven by PDGF and those driven by loss of combined NF1 and PTEN or EGFRvIII39." (PMID 32532995, 2020). "A high frequency of mutations in IDH1 and Chr1p19q was detected in gliomas with low PIEZO1 expression, while mutations in TTN, PTEN and NF1 were significantly enriched in cases with high expression of PIEZO1." (PMID 32999349, 2020). "For example, oligodendrocyte precursor cells (OPCs) have been identified as the cell of origin for gliomas in Nf1 conditional knockout mice, with Nf1 mutant mice expressing more OPCs in the brain." (PMID 32074109, 2020).
glioma (continued). "Detection of a BRAF V600E mutation next to mutations in NF1 and JAK3 as well as deletions of KIT and PDGFRA led to the diagnosis of a pediatric-type low-grade glioma or ganglioglioma." (PMID 32758285, 2020). "Taken together, these findings demonstrate that a major role for ASCL1 in the Nf1;Tp53CKO glioma mouse model is to drive tumor cell proliferation." (PMID 32573857, 2020). "In summary, our results show, for the first time, the NF1-LRD domain reverts NF1-loss induced invasion, and provides initial evidence into the otherwise novel function of NF1-LRD in glioma biology." (PMID 30967630, 2019). "The association of PA with NF1 has been recognized for many years, and PA constitutes one of the most common types of gliomas in patients with NF1." (PMID 29983406, 2019). "Our assumption is based on the observation that point mutations generated within the NF1-LRD domain (D1849N and W1952*) abolished cell invasion of glioma cells lines and non-NF1-patient-derived glioma cells." (PMID 30967630, 2019). "U87MG human glioma cells expressing functional neurofibromin were first transduced with NF1-shRNAs followed by transduction of either pCDH vector or pCDH-NF1-LRD." (PMID 30967630, 2019). "In the NF1-glioma cohort, median overall survival for patients with an ALT-positive tumor was only 18 months and significantly differed compared to patients with either long (69 months) or normal telomeres (not reached) (p < 0.0001, log rank test)." (PMID 31462295, 2019). "NF1 expression was knocked down using two independent lentiviral shRNAs in two NF1-expressing patient-derived glioma propagating cells (GPCs)." (PMID 30967630, 2019). "Syndromic NF1 germline mutations, similar to syndromic TSC1/2 mutations, are associated with low-grade gliomas that nevertheless differ in morphological appearance, with NF1 usually associated with pilocytic astrocytoma, and TSC with SEGA." (PMID 31258848, 2019). "In comparison to the vector control, overexpression of NF1-LRD in LN229 human glioma cells reduced invasion by approximately 80%." (PMID 30967630, 2019). "Taken together, our results show, for the first time, that NF1-LRD inhibits glioma invasion, and provides evidence of a previously unrecognized function of NF1-LRD in glioma biology." (PMID 30967630, 2019). "The Ras classifier was able to detect NF1-loss events particularly well in CNS tumors (GBM, low-grade glioma [LGG], and pheochromocytoma and paraganglioma [PCPG])." (PMID 29617658, 2018). "To identify changes in the production of secreted cytokines/chemokines in NF1 deficient glioma, we applied cytokine arrays to conditioned media from a panel of three GBM cell lines after siRNA-mediated NF1 knockdown." (PMID 29643433, 2018). "As clinical next-generation sequencing for brain tumors becomes more common, more NF1-altered gliomas will be identified, and the identification of such tumors will be critical for further study." (PMID 29643433, 2018). "NF1 knockdown under our experimental conditions resulted in increased secretion of surprisingly few cytokines and chemokines in the glioma cell lines." (PMID 29643433, 2018). "The differences across these genes are well summarized by NF1 community scores, where glioma cell lines with intact NF1 consistently score above glioma cell lines with NF1 loss of function (Wilcoxon rank‐sum P = 0.005)." (PMID 30573688, 2018). "Compared to diffusely infiltrating gliomas with intact NF1, lower grade gliomas with NF1 alteration have a worse prognosis, while GBM with NF1 alteration has a similar clinical outcome to cases without NF1 alterations." (PMID 29643433, 2018).
glioma (continued). "Future mechanistic studies will be required to address the relationships between NF1/RAS/MEK/ERK pathway function, ETV5 network regulation, and NF1-associated low-grade glioma formation or maintenance." (PMID 29787563, 2018). "Analysis of The Cancer Genome Atlas confirmed a relationship between glioma NF1 status and ENG and CHI3L1 in tumor samples." (PMID 29643433, 2018). "It should be noted that mutations of NF1 and PTEN were almost exclusive to IDH-wildtype glioma, indicating the functional importance of increased NF1 and PTEN expression in IDH-mutant glioma." (PMID 27852048, 2017). "Evidence from several different experimental studies has revealed a critical role for the tumor microenvironment in murine Nf1 optic glioma formation and growth." (PMID 28066715, 2016). "MiR-9 was highly expressed in glioma and promoted the invasion of glioma cells by directly targeting NF1 messenger." (PMID 26646588, 2016). "Losses and mutations of NF1 and PTEN, as well as amplification and mutation of PIK3CA were preferentially found in the RMPAhigh gliomas." (PMID 27385209, 2016). "Sex differences in expression and function of cAMP regulators have also been demonstrated in glioma precursor cells derived from a mouse model of NF1." (PMID 26283963, 2015). "Between 15 and 50 % of NF1 patients develop some type of glioma; these are often indolent in nature." (PMID 26666878, 2015). "The relevance of NF1 to human high-grade gliomas was further validated when the TCGA identified NF1 as the defining mutation for the mesenchymal subtype of glioblastoma in a multi-dimensional genomic analysis." (PMID 23762429, 2013). "In sporadic low-grade gliomas driven by KIAA1549:BRAF and familial low-grade gliomas associated with protein neurofibromin 1 (NF1), mTOR represents a central growth control target." (PMID 23717811, 2013). "Increased c-Jun-NH2-kinase signaling in neurofibromatosis-1 heterozygous (Nf1+/−) microglia was shown to promote optic glioma proliferation and glioma growth." (PMID 23983766, 2013). "In rescue experiments, NF1 knockdown restored the migration capability of T98G cells with miR-9 knocked down, suggesting that miR-9 modulates the migration capacity of glioma cells at least partly by targeting NF1." (PMID 23185366, 2012). "Because both CREB and miR-9 are highly expressed in glioma cells compared with normal glial cells, the NF1 protein level is determined by the balance between them." (PMID 23185366, 2012). "As a result, the balance shifts toward miR-9 and the expression of NF1 is restrained in these glioma cells." (PMID 23185366, 2012).